BCL2L2 (BCL2 like 2)
Description:
Promotes cell survival. Blocks dexamethasone-induced apoptosis. Mediates survival of postmitotic Sertoli cells by suppressing death-promoting activity of BAX.
Synonyms: Bcl2-L-2; BCLW; KIAA0271; BCL-W; PPP1R51
Tractability: Small molecule: a drug acting on it is in phase 2 or 3 trials; a high-quality ligand is known; it has a high-quality binding pocket; it belongs to a druggable protein family. Antibody: UniProt places it where antibodies can reach, with high confidence. PROTAC: ubiquitination databases record sites on it; a small molecule that binds it is known.
Target class: Other cytosolic protein
Gene: Protein-coding gene on chromosome 14 (23,298,790 to 23,313,069, forward strand). Ensembl gene ENSG00000129473.
Subcellular location: Mitochondrion membrane
Subcellular location (Human Protein Atlas): Nucleoplasm
Gene Ontology:
Molecular function: disordered domain specific binding; identical protein binding; protein binding; channel activity
Biological process: negative regulation of apoptotic process; regulation of apoptotic process; extrinsic apoptotic signaling pathway in absence of ligand; intrinsic apoptotic signaling pathway in response to DNA damage; positive regulation of apoptotic process; release of cytochrome c from mitochondria; spermatogenesis; developmental process involved in reproduction; transmembrane transport
Cellular component: Bcl-2 family protein complex; mitochondrion; mitochondrial outer membrane; cytosol; mitochondrial membrane
Genetic constraint (gnomAD): Loss-of-function variants: 6 observed, 13.41 expected, observed/expected ratio (o/e) 0.45, 90% interval 0.24 to 0.88. The upper end of that interval is the gene's LOEUF score, 0.88, which puts it in group 3 of 6, group 1 being the genes least tolerant of losing a copy. Missense variants: 191 observed, 235.82 expected, observed/expected ratio (o/e) 0.81, 90% interval 0.72 to 0.91. Synonymous variants: 90 observed, 95.35 expected, observed/expected ratio (o/e) 0.94, 90% interval 0.8 to 1.12.
Homologues: Orthologues: guinea pig BCL2L2 (99% identical), pig BCL2L2 (99% identical), mouse Bcl2l2 (98% identical), rabbit BCL2L2 (93% identical), rat Bcl2l2 (79% identical), tropical clawed frog bcl2l2 (66% identical). Paralogues in human: BCL2L1 (49% identical), BCL2 (41% identical), BAK1 (24% identical), MCL1 (21% identical), BOK (20% identical), BAX (19% identical), BCL2A1 (16% identical), BCL2L10 (16% identical).
Diseases named in the same sentence as BCL2L2 in open-access papers:
BCL2L2 is named in the same sentence as 56 diseases in open-access papers, as found by Europe PMC text mining. Sharing a sentence is not in itself a finding about the gene and the disease. The quoted sentences say what the papers report.
ovarian carcinoma (13 papers, 2018 to 2023). A malignant neoplasm originating from the surface ovarian epithelium. "In ovarian cancer, increased miR-335 expression was associated with increased sensitivity to cisplatin through its target gene BCL2L2, an anti-apoptotic protein increased in several cancer types." (PMID 38203360, 2023). "Our study was designed to explore the association miR‐335‐5p and BCL2L2 and to investigate the influence of miR‐335‐5p/BCL2L2 axis on cisplatin‐resistant ovarian cancer cells." (PMID 30019389, 2018). "Inhibition of SF3B1 induces ovarian cancer cell pyroptosis by splicing regulation of BCL2L2, resulting in the release of mtDNA." (PMID 38012150, 2023). "In summary, we concluded that BCL2L2 is a direct target gene of SF3B1 and that the inhibition of SF3B1 induces ovarian cancer cell pyroptosis at least partly through BCL2L2." (PMID 38012150, 2023). "The inhibition of BCL2L2 results in the high expression of miR-335-5p, which increases cisplatin sensitivity in ovarian cancer." (PMID 36829221, 2023). "RT-qPCR was performed to detect the expression levels of miR-335 and BCL2L2 in ovarian cancer cells and tissues." (PMID 34090463, 2021). "By directly binding to the 3′-UTR of BCL2L2 and inhibiting its expression, miR-335-5p has been shown to restored cisplatin sensitivity in ovarian cancer cells." (PMID 33414429, 2021). "In a word, XIST can inhibit the activity of ovarian cancer cells by regulation of BCL2L2 and miR-335." (PMID 34090463, 2021). "In this study, we reported the interaction between XIST and miR-335, which regulates the growth of ovarian cancer cells by targeting BCL2L2 directly." (PMID 34090463, 2021). "On the contrary, BCL2L2 was upregulated in ovarian cancer compared to matched adjacent normal tissues (p<0.01)." (PMID 34090463, 2021). "It was reported that ectopic BCL2L2 expression almost fully nullified the inhibitory effect of miR-335 on migration and invasion of ovarian cancer cells." (PMID 32317622, 2020). "Based upon the prior findings above and a study of Cao et al11 concerning the relationship between miR‐335 and Bcl‐w protein, we decided to elaborate on the impacts of miR‐335‐5p/BCL2L2 axis on cisplatin‐resistant ovarian cancer cells." (PMID 30019389, 2018). "Overexpression of miR‐335‐5p significantly reduced the expression of BCL2L2, decreasing the cell viability, and improving apoptosis of cisplatin‐resistant ovarian cancer cell A2780/DDP." (PMID 30019389, 2018). "Using an online prediction algorithm to hunt for miR-335 control targets that may involve in ovarian cancer proceeding, BCL2L2 has been identified, which has a supposed miR-335 combining site in 3′UTR." (PMID 34090463, 2021). "We next studied the relationship between XIST and BCL2L2 in ovarian cancer cell lines." (PMID 34090463, 2021). "The XIST/miR-335/BCL2L2 axis determined in our study might provide potential treatment strategies for ovarian cancer." (PMID 34090463, 2021). "In addition, the expression level of miR-335 and BCL2L2 in clinical ovarian cancer samples was significantly negatively correlated." (PMID 34090463, 2021). "Likewise targeting the same BCL2L2 gene, it is capable of inhibiting invasiveness in ovarian cancer." (PMID 32582296, 2020). "This study aims to probe into whether there is a targeting relationship between miR‐335‐5p and BCL2L2 mRNA and how their interaction regulates the cisplatin resistance of ovarian cancer cells." (PMID 30019389, 2018). "In summary, we validated the targeted relationship between BCL2L2 and miR‐335‐5p in ovarian cancer." (PMID 30019389, 2018). "Last but not least, our study verified that miR‐335‐5p could enhance the cisplatin sensitivity of cisplatin‐resistant ovarian cancer cells via downregulation of BCL2L2 expression." (PMID 30019389, 2018).
ovarian carcinoma (continued). "Upregulation of miR‐335‐5p expression enhanced the cisplatin sensitivity of ovarian cancer cells through suppressing BCL2L2, suggesting the potential of miR‐335‐5p/BCL2L2 axis as a therapeutic target for the cisplatin resistance of patients with ovarian cancer." (PMID 30019389, 2018). "In addition, the miR-335/BCL2L2 axis was involved in the functions of XIST in ovarian cancer cells." (PMID 34090463, 2021). "Additionally, BCL2L2 was found overexpressed in ovarian cancer cells, which had been also reported in a study of Li et al14 on the relationship between miRNA‐21 and Bcl‐2 where Bcl‐2 protein expression is drastically upregulated in ovarian cancer cells in comparison with normal ovarian tissues." (PMID 30019389, 2018). "In order to further verify the connection of XIST, miR-335, and BCL2L2 in ovarian cancer, the levels of XIST, miR-335, and BCL2L2 were measured." (PMID 34090463, 2021). "When BCL2L2 expression was inhibited by miR‐335‐5p, the DDP resistance of ovarian cancer cells was significantly alleviated, resulting in an accelerating cell apoptosis and cell cycle arrest at G1 phase." (PMID 30019389, 2018). "In another example, miR-142-5p targeted several antiapoptotic genes, including baculoviral IAP repeat-containing 3 (BIRC3), B-cell lymphoma-2 (BCL2), BCL2-like 2 (BCL2L2), and myeloid cell leukemia sequence 1 (MCL1), and could improve cisplatin-mediated anticancer function in ovarian cancer." (PMID 31861383, 2019).
breast cancer (10 papers, 2014 to 2025). A primary or metastatic malignant neoplasm involving the breast. "For example, HOTAIR is a ceRNA for miR-206 and increases the expression of a miR-206 target gene, the Bcl-w/Bcl-2 like protein 2 (BCL2L2) gene, thus promoting breast cancer proliferation." (PMID 32486413, 2020). "Its upregulation suppresses breast cancer cell proliferation and induces its apoptosis, while downregulation, via hypermethylation, increases breast cancer progression due to BCL2L2 overexpression." (PMID 32512929, 2020). "The induction of antiapoptotic genes, including B-cell CLL/lymphoma 2 (BCL2), BCL2 related protein A1 (BCL2A1), BCL2 like 1 (BCL2L1), BCL2L2, and myeloid cell leukemia 1 (MCL1), has been observed in multiple cancers, including breast cancer." (PMID 36853387, 2023). "ABT-737 is an inhibitor of BCL-XL (BCL2L1), BCL-w (BCL2L2), and BCL-2 that has been shown to enhance cell death, including in MCF7 breast cancer cells and myeloma cells by binding and inhibiting the activity of antiapoptotic BCL2 family members." (PMID 24745479, 2014). "The five antiapoptotic genes (BCL2, BCL2A1, BCL2L1, BCL2L2, and MCL1) are frequently overexpressed in ER-positive breast cancer cells, and these genes have been used as clinical biomarkers in the diagnosis of breast cancer." (PMID 36853387, 2023). "Here, we revealed that BCL2, BCL2A1, BCL2L2, and MCL1 but not BCL2L1 were overexpressed in estrogen receptor (ER)-positive breast cancer cells and clinical biopsies." (PMID 36853387, 2023).
colon cancer (7 papers, 2014 to 2025). "For example, it has been reported that miR-195 plays a positive effect on the chemotherapy sensitivity of doxorubicin in colon cancer cells by targeting the first binding site of BCL2L2 mRNA." (PMID 29228608, 2017). "BCL2L2 was determined to promote tumorigenicity and invasion in human glioblastoma, non-small-cell lung cancer, and colon cancer." (PMID 28694563, 2017). "Previous studies have shown that ectopic expression of miR-195 also sensitized glioblastoma, hepatocellular carcinoma, breast cancer, and colon tumor cells to temozolomide, 5-fluorouracil, adriamycin, and doxorubicin treatment by targeting BCL2L-2, BCL-W, and RAF-1 genes, respectively." (PMID 29126391, 2017). "This epigenetic modification leads to the downregulation of the anti-apoptotic gene BCL2-like 2 (BCL2L2/BCL-W), ultimately inducing apoptosis in human HCT116 colon cancer cells." (PMID 40508066, 2025). "The analysis of gene expression considered five genes associated with apoptosis—BCL2 (B-cell CLL/lymphoma 2), BCL2L1 (BCL2 Like 1), BCL2L2 (BCL2 Like 2), CASP3 (caspase 3), and CASP9 (caspase 9), and was carried out in human colon cancer cells exposed to the IC50 dose of BVR." (PMID 38732003, 2024).
lung cancer (7 papers, 2012 to 2023). A malignant neoplasm involving the lung. "By regulating the expression of MCL-1 and BCL2L2, mir-133b is associated with lung cancer, which was also observed in our results." (PMID 26508990, 2015). "BCL2L2 amplification in non–small cell lung cancer has been associated with poor prognosis." (PMID 25126591, 2014). "MicroRNA-133a, downregulated in osteosarcoma, suppresses proliferation and promotes apoptosis by targeting Bcl-xL and Mcl-1; miRNA-133b targets pro-survival molecules MCL-1 and BCL2L2 in lung cancer." (PMID 32309578, 2016). "miR-133b targets MET in CRC cells; PKM2 in tongue SCC; FSCN1 in ESCC and myeloid cell leukemia sequence 1 (MCL1); and BCL2-like 2 (BCL2L2) in lung cancer." (PMID 22308266, 2012). "Evidence shows that over-expression of miR-133b also reduces the expressions of both BCL2L2 and MCL-1 and induces apoptosis in lung cancer cell lines." (PMID 24391788, 2013).
gastric cancer (6 papers, 2015 to 2025). A primary or metastatic malignant neoplasm involving the stomach. "It is known that MIR335 negatively regulates the metastasis in gastric cancer by targeting BCL2L2 and SP1." (PMID 32582296, 2020). "We previously reported that BCL2L2 enhances the migratory and invasive potentials of gastric cancer cells by facilitating the production of several types of extracellular matrix (ECM)-degrading proteinases." (PMID 26155940, 2015). "BCL2L2 is expressed in various cancer types-including gastric cancer, colorectal adenocarcinomas, and GBM-in a cancer cell-specific manner." (PMID 26155940, 2015). "It has been reported previously that CTNND1, EZH2, BCL2L2, CDH2, VIM, and EGFR have positive correlation to proliferation, invasion, and poor prognosis of gastric cancer." (PMID 28694563, 2017).
glioblastoma (6 papers, 2015 to 2025). The most malignant astrocytic tumor (WHO grade IV). "Bcl2l2‐Pabpn1 encodes a fusion protein and promotes glioblastoma progression through blocking Bax and activating PI3K/AKT pathway." (PMID 35894779, 2022). "Together, our work characterized a glioblastoma‐associated Bcl2l2‐Pabpn1 fusion transcript shared by humans and rats." (PMID 35894779, 2022). "Downregulation of Bcl2l2‐Pabpn1 arrested the cell cycle at the G2‐M phase in glioblastoma cells, indicating that reduced proliferation activity induced by Bcl2l2‐Pabpn1 deficiency might be related to G2‐M phase cell cycle arrest." (PMID 35894779, 2022). "To examine the effects of Bcl2l2‐Pabpn1 on glioblastoma development, we designed two shRNAs targeting the fusion junction of Bcl2l2‐Pabpn1 read‐through fusion transcript (NM_001199864.3)." (PMID 35894779, 2022). "Bcl2l2, an oncogene, has been reported to promote cell proliferation, migration and invasion in various tumours, including glioblastoma." (PMID 35894779, 2022). "The expression of Bcl2l2‐Pabpn1 needs to be examined in glioblastoma and normal tissues by further experiments." (PMID 35894779, 2022). "Collectively, Bcl2l2‐Pabpn1 is a read‐through fusion transcript shared by humans and rats, and present in normal astrocytes and glioblastoma cells." (PMID 35894779, 2022). "Unexpectedly, our findings showed Bcl2l2‐Pabpn1 fusion was expressed not only in glioblastoma cell lines but also in normal astrocytes." (PMID 35894779, 2022). "In this study, we identified Bcl2l2‐Pabpn1 fusion transcript not only in glioblastoma cells but also in normal cells, and this fusion is shared by humans and rats." (PMID 35894779, 2022). "Hypomethylation status of BCL2L2 was frequently observed in patients with glioblastoma multiforme (GBM), which exerted a high proliferation index and low sensitivity to apoptosis." (PMID 32317622, 2020). "Potential targets of gossypol in glioblastoma TS were BCL2L2 (Bcl2 like 2), MCL1 (Myeloid cell leukemia 1), APEX, and several dehydrogenases." (PMID 31658771, 2019). "Collectively, these findings indicated that Bcl2l2‐ Pabpn1 fusion transcript might be a novel regulator of proliferation, migration and invasion in glioblastoma." (PMID 35894779, 2022). "Interestingly, Bcl2l2‐Pabpn1 fusion found in rat cells was also expressed in human glioblastoma and normal cells in our study." (PMID 35894779, 2022). "In addition, BCL2L2 potentiates aggressiveness, stemness, and a mesenchymal phenotype in glioblastoma cells by inducing the nuclear translocation of β-catenin." (PMID 26155940, 2015). "We further explored whether Bcl2l2‐Pabpn1 participates in the motility of glioblastoma cells." (PMID 35894779, 2022). "In the present study, Bcl2l2‐Pabpn1 knockdown significantly restricted the proliferation, migration, invasion and EMT of human glioblastoma cells." (PMID 35894779, 2022). "Mechanistically, Bcl2l2‐Pabpn1 blocked Bax activity and activated PI3K/AKT pathway to promote glioblastoma progression." (PMID 35894779, 2022). "Unlike other fusions reported in glioblastoma, Bcl2l2‐Pabpn1 appeared to result from RNA processing rather than genomic rearrangement." (PMID 35894779, 2022). "Although Bcl2l2‐Pabpn1 fusion is not unique to cancer and is not a candidate biomarker of glioblastoma, our work may provide a new idea for therapeutic intervention of glioblastoma." (PMID 35894779, 2022).
osteosarcoma (6 papers, 2013 to 2020). A usually aggressive malignant bone-forming mesenchymal neoplasm, predominantly affecting adolescents and young adults. "Taken together, these results demonstrated that down-regulated miR-422a promoted the pathogenesis of osteosarcoma by increasing the expression of its target genes BCL2L2 and KRAS." (PMID 29358307, 2018). "Over-expression of miR-133b in osteosarcoma cell lines U2-OS and MG-63 decreases the expression of BCL2L2, MCL-1, IGF1R, MET and FAK, leading to the inactivation of Akt." (PMID 24391788, 2013). "Further, to better understand the mechanisms how miR-133b regulates cellular phenotypes of osteosarcoma cells, we first measured the expression of BCL2L2, MCL-1, IGF1R and MET, which are identified as the target genes of miR-133b in several cancers." (PMID 24391788, 2013). "Taken together, the present study demonstrates that miR-422a may serve as a tumor suppressor in osteosarcoma via inhibiting BCL2L2 and KRAS translation both in vitro and in vivo." (PMID 29358307, 2018). "BCL2L2 amplification in osteosarcoma has not been reported previously, but 25% of osteosarcomas express the related protein Bcl-2, which has been linked with decreased long-term survival." (PMID 25126591, 2014). "Taken together, these data demonstrated that miR-422a exhibited its anti-tumor effects probably through inhibiting the protein expression of BCL2L2 and KRAS in osteosarcoma cells." (PMID 29358307, 2018). "These indicate that miR-133b play a role as a tumor suppressor gene in osteosarcoma through inhibiting PI3K/Akt signaling and down-regulating several anti-apoptotic molecules and oncogenes such as BCL2L2, MCL-1, IGF1R, MET, and FAK." (PMID 24391788, 2013). "Results showed that expression of BCL2L2, MCL-1, IGF1R, MET, phospho-Akt and FAK were significantly decreased in miR-133b over-expressed osteosarcoma cell lines U2-OS and MG-63." (PMID 24391788, 2013). "The western blotting results showed that over-expression of miR-133b decreased the expression of BCL2L2, MCL-1, IGF1R and MET in osteosarcoma cells U2-OS and MG-63." (PMID 24391788, 2013). "Therefore, we explored the relationship between miR-422a and its targets BCL2L2 and KRAS in osteosarcoma." (PMID 29358307, 2018). "Furthermore, restoration of miR-422a and knockdown of BCL2L2 and KRAS promoted apoptosis and induce cell cycle arrest in osteosarcoma cells." (PMID 29358307, 2018). "The decrease expression of anti-apoptotic molecules BCL2L2 (Bcl-w) and MCL-1 may contributes to the increasing apoptosis of osteosarcoma cells." (PMID 24391788, 2013). "In addition, miR-422a decreased the protein expression of BCL2L2 and KRAS while the mRNA levels remained unchanged, suggesting that miR-422a exhibited the anti-tumor effect via regulating BCL2L2 and KRAS protein expression in osteosarcoma cells." (PMID 29358307, 2018). "Therefore, the modulation of BCL2L2 and KRAS by miR-422a may explain why the down-regulation of miR-422a during osteosarcoma carcinogenesis can promote cancer progression." (PMID 29358307, 2018).
bladder cancer (4 papers, 2017 to 2025). "Another previous study reported elevated expression of the cis-SAGes BCL2L2-PABPN1 and CHFR-GOLGA3, predominantly localized in the nucleus, in bladder cancer." (PMID 41155268, 2025). "Notably, BCL2L2-PABPN1 chimeric RNA, which was generated by cis-splicing of adjacent genes, was detected at significantly higher level in bladder cancer specimens than in normal cells." (PMID 32317622, 2020).
cervical cancer (4 papers, 2015 to 2025). A primary or metastatic malignant neoplasm involving the cervix. "Ectopic expression of miRNA-214 reduces cell survival, induces apoptosis, and enhances sensitivity to CDDP through directly inhibiting BCL2-like 2 (Bcl2l2) expression in cervical cancer HeLa and C-33A cells." (PMID 30744689, 2019). "On the other hand, miR-214 enhanced the cisplatin-induced cytotoxicity through down-regulation of Bcl2l2 in cervical cancer cells." (PMID 26666173, 2015).